KRT18 (keratin 18)
Diseases named in the same sentence as KRT18 in open-access papers (continued):
Sharing a sentence is not in itself a finding about the gene and the disease.
chordoma (4 papers, 2014 to 2025). Chordomas are rare malignant tumors arising from embryonic remnants of the notochord in axial skeleton. "Genes marked on the volcano plot were either implicated earlier in chordoma biology (e.g. keratins—KRT8, KRT18, KRT19, TBXT, LMX1A, and EGFR) or identified by outstanding p-value (e.g. IL11, CD24), high absolute fold-change (e.g. GABRA1) or DMR result (e.g. MNX1)." (PMID 37434245, 2023). "Indeed, chordoma was originally described as one of the unique “triple positive” EMA/S100 protein/keratins neoplasia in bone and soft tissue pathology and diffuse immunostaining for wide spectrum cytokeratins, cytokeratin-8, cytokeratin-19, and cytokeratin-18 was demonstrated in this tumour." (PMID 24591762, 2014).
injury (4 papers, 2017 to 2025). Damage inflicted on the body as the direct or indirect result of an external force, with or without disruption of structural continuity. "Here we show that by measuring a circulating biomarker, cytokeratin-18 (K18), accurate detection of drug-induced liver injury (DILI) is possible." (PMID 40617841, 2025).
liver dysfunction (4 papers, 2009 to 2023). "This upregulation of miR-122 is positively correlated with the degree of inflammation and fibrosis and serves as a valuable indicator of NAFLD severity in various stages of liver dysfunction alongside traditional liver markers such as aspartate aminotransferase (AST) and cytokeratin-18 (CK18)." (PMID 37371692, 2023).
metastatic cancer (4 papers, 2021 to 2024). A carcinoma which has spread from the original site of growth to another anatomic site. "Results revealed a higher Mesenchymal markers in primary cancer cells (e.g., NCAM1, LAMB1, SERPINE1, TCF4, VIM, ZEB1, and ZEB2) and a higher Epithelial markers in metastatic cancer cells (e.g., CDH1, CLDN4, ELF3, EPCAM, KRT18, KRT7, and KRT8)." (PMID 37202394, 2023).
ulcerative colitis (4 papers, 2011 to 2024). An inflammatory bowel disease involving the mucosal surface of the large intestine and rectum. "The objective of this study was to determine serum levels of the M30 fragment of cytokeratin 18 and its utility as an activation marker in patients with ulcerative colitis, who are known to have increased apoptosis." (PMID 39292076, 2024).
alcoholic liver diseases (3 papers, 2012 to 2023). A disorder caused by damage to the liver parenchyma due to alcohol consumption. "Imbalance in KRT8/KRT18 expression occurs in alcoholic liver disease (ALD) and promotes MDB formation." (PMID 34063343, 2021).
alcoholic steatohepatitis (3 papers, 2021 to 2022). "In the case of alcoholic steatohepatitis, the spectrum of currently established biomarkers is much more limited, with the M30 and M65 epitopes of cytokeratin-18 (CK18) having the widest support in the literature." (PMID 36558425, 2022). "Composed primarily of aggregated KRT8 and lesser amounts of KRT18, MDBs are cytoplasmic inclusions that occur within hepatocytes most frequently in alcoholic steatohepatitis (ASH) or alcoholic cirrhosis." (PMID 35637421, 2022). "Ubiquitinated KRT18, KRT8, and sequestosome 1/p62 are the main components of Mallory–Denk bodies (MDB) specific for alcoholic steatohepatitis and NASH." (PMID 34063343, 2021).
asthma (3 papers, 2012 to 2021). "Recently, increased incidence of antinuclear antibodies and autoantibodies against bronchial epithelial or endothelial antigens have been found in asthma patients, such as autoantibodies against cytokeratin-18, alpha-enolase and IgE." (PMID 22698187, 2012). "A study identified KRT18 as a bronchial epithelial autoantigen that is associated with adulthood nonallergic asthma." (PMID 26672748, 2015).
cholestasis (3 papers, 2017 to 2021). Impairment of the bile flow caused by obstruction within the liver, or outside the liver in the bile duct system. "This was previously demonstrated in a pre-clinical rodent study where plasma levels of K18, miR-122 and HMGB1 increased progressively after bile duct ligation (cholestasis) while caspase-cleaved cytokeratin-18 fragments (c K18) did not increase, indicating cell necrosis and the absence of apoptosis." (PMID 30873474, 2017).
cholesteatoma (3 papers, 2012 to 2018). A pathologic process characterized by the proliferation of keratinizing squamous epithelium resulting in the accumulation of keratin and cells in the middle ear and/or mastoid. "KRT18 and 19 mRNA have also been found to be increased in cholesteatoma compared with retroauricular skin and EACS." (PMID 25093596, 2014). "The analysis of the cytokeratin-expression revealed an up-regulation of Keratin 6 A and B, Keratin 18, Keratin 19 and Keratin 81 in cholesteatoma compared to normal skin." (PMID 23285167, 2012).
chondrosarcoma (3 papers, 2014 to 2023). A malignant cartilaginous matrix-producing mesenchymal neoplasm arising from the bone and soft tissue. "Immunohistochemical analysis of human mesenchymal chondrosarcoma cases also showed positive expressions of CK18 and GAL3, gene products of KRT18 and LGALS3, respectively." (PMID 37212282, 2023). "Expression of Krt8, Krt18, and Lgals3, which are notochord markers, was observed in cluster 6, suggesting that dysregulated differentiation might also occur in mesenchymal chondrosarcoma, unlike normal chondrocytic differentiation." (PMID 37212282, 2023).
coronary artery disease (3 papers, 2017 to 2025). "The aim of this study was to determine the gene expression and protein levels of interleukin‐33 (IL‐33), fetuin A and cytokeratin 18 (CK‐18) in the pericardial fluid (PF) and plasma of patients with coronary artery disease (CAD) undergoing coronary artery bypass grafting (CABG)." (PMID 40437664, 2025).
endometriosis (3 papers, 2019 to 2024). The growth of functional endometrial tissue in anatomic sites outside the uterine body. "In parallel with the predecidua changes, various CEC types isolated from patients with endometriosis in our cohort showed different gene expression profiles, represented by typically elevated gene expression of KRT18, NANOG, and VIM or of KRT19 and ESR1." (PMID 31717910, 2019). "There were several genes strongly expressed in endometriosis tissue: EPCAM, KRT18, WT1, MUC16, MUC1, and ESR1, if compared to the endometrial cells from healthy controls." (PMID 31717910, 2019). "The genes with increased expression (KRT18, KRT19, VIM, and NANOG) were then used in subsequent analyses as “endometriosis confirmatory genes”." (PMID 31717910, 2019).
gastric adenocarcinoma (3 papers, 2018 to 2021). "In the present study, we analyzed the expression level of KRT18 in 450 stomach adenocarcinoma tissue samples from TCGA database and found a significantly higher expression level in tumor tissues." (PMID 34290732, 2021). "We then explored the potential functions of KRT18 in AGS cells (human gastric adenocarcinoma cell line) by KRT18 knockdown using siRNA and whole transcriptome RNA-seq analysis." (PMID 34290732, 2021). "In the present study, we analyzed the expression level of KRT18 in 450 stomach adenocarcinoma (STAD) tissue samples available in TCGA database, showing a significant increase in cancer samples." (PMID 34290732, 2021). "We then explored the potential functions of KRT18 in GC AGS cells (human gastric adenocarcinoma cell line) using siRNA to knockdown KRT18 expression." (PMID 34290732, 2021).
Gastric tumors (3 papers, 2010 to 2021). "We analyzed the expression level of KRT18 in 450 STAD tissue samples from TCGA database and 140 GC samples from GEO database and found a significant overexpression in gastric tumor samples, consistent with the biomarker function of KRT18 in GC." (PMID 34290732, 2021). "We then used the RNA-seq data of gastric tumor samples to further analyze the potential impact of KRT18 on AS regulation of cancer transcriptome." (PMID 34290732, 2021).
lymphoma (3 papers, 2011 to 2022). A malignant (clonal) proliferation of B- lymphocytes or T- lymphocytes which involves the lymph nodes, bone marrow and/or extranodal sites. "Cytokeratin 18 is not expressed in lymphoma cells so is a potential biomarker of epithelial toxicity in this setting." (PMID 21245866, 2011).
metastatic prostate carcinoma (3 papers, 2012 to 2026). A carcinoma that arises from the prostate gland and has spread to other anatomic sites. "Our study establishes the existence and clinical relevance of CD45+CK18+ (PTPRC+KRT18+) hybrid CTC-like cells in metastatic prostate cancer." (PMID 41355965, 2026). "An enzalutamide-refractory metastatic prostate cancer patient with lymph node involvement exhibited intratumoral infiltration of activated NK cells and had a 70% induction of serum caspase-cleaved cytokeratin-18 72 h after the first dose of 625 mg ONC201." (PMID 31118108, 2019). "This study aimed to characterize circulating hybrid cells co-expressing KRT18 (pan-cytokeratin) and PTPRC (CD45), termed KP_Pos, in metastatic prostate cancer (mPCa), and to assess their molecular features, tumor microenvironmental (TME) origins, and clinical relevance." (PMID 41355965, 2026).
Abdominal obesity (2 papers, 2020 to 2023). Excessive fat around the stomach and abdomen. "In the presented study, the cytokeratin-18 fragment plasma level was elevated in obese compared to overweight patients and was strongly associated with liver injury markers, such as ALT, FLI and GGT, as well as with indexes of abdominal obesity." (PMID 37189422, 2023).
acute pancreatitis (2 papers, 2014 to 2022). An acute inflammatory process that leads to necrosis of the pancreatic parenchyma. "The study found that the expression of Krt18 was significantly increased in mild acute pancreatitis." (PMID 36671463, 2022).
ameloblastoma (2 papers, 2008 to 2018). The most common odontogenic tumor, arising from the epithelial component of the embryonic tooth and usually affecting the molar-ramus region of the mandible or maxilla. "Immunocytochemistry revealed that the cultured ameloblastoma cells expressed normal levels of cytokeratins 14 and 16 and only weakly expressed cytokeratin 18 and vimentin, indicating that these cultures were primarily comprised of ameloblastoma cells of epithelial origin." (PMID 18588710, 2008).
biliary tract cancer (2 papers, 2015 to 2018). "In this study, we determined the efficacy of the cell death biomarker cytokeratin 18 for diagnosing biliary tract cancer (BTC)." (PMID 30451962, 2018).
cervical squamous cell carcinoma (2 papers, 2012 to 2025). A squamous cell carcinoma arising from the cervical epithelium. "Inhibin alpha and cytokeratin 18 are particularly helpful in distinguishing ETT from cervical squamous cell carcinoma (SCC), which does not express these proteins." (PMID 23243530, 2012).
chronic heart failure (2 papers, 2020 to 2024). "We found that amiodarone-treated patients with chronic heart failure revealed significantly higher serum levels of caspase-cleaved keratin-18, an apoptosis biomarker, compared to healthy individuals or patients not receiving amiodarone." (PMID 32651653, 2020). "We found that amiodarone-treated patients with chronic heart failure revealed significantly higher serum levels of caspase-cleaved keratin-18 compared to healthy individuals or patients not receiving amiodarone." (PMID 32651653, 2020).
chronic liver failure (2 papers, 2017 to 2022). Liver failure that develops slowly and gradually for some time, possibly for years, often as the result of cirrhosis, or malnutrition. "In line with previous observations in patients with acute-on-chronic liver failure, we find an association of cytokeratin-18 and its caspase‐cleaved fragments with the development of acute decompensation in patients with chronic liver disease." (PMID 35176084, 2022).
E. coli infection (2 papers, 2015 to 2021). "The expression of six genes (KRT18, ARPC5L, ACTG1, ARPC2, EZR, and YWHAZ) related to pathogenic E. coli infection was simultaneously increased with TNFRSF11B overexpression via gene set enrichment analysis (GSEA)." (PMID 34938284, 2021). "In addition, only six genes (KRT18, ARPC5L, ACTG1, ARPC2, EZR, and YWHAZ) related to pathogenic E. coli infection were simultaneously increased in both GSEA studies; these genes are mostly involved in focal adhesion, as determined via GO analysis." (PMID 34938284, 2021). "However RRMS clinic subtype patients also show an increase in the ACTB, KRT18, FYN, TUBA4A, NCL, CTNNB1 proteins which are a part of pathogenic E. coli infection pathway, which induce the mobilization of inflammatory cells." (PMID 25942430, 2015).
embryonal carcinoma (2 papers, 2008 to 2021). A non-seminomatous malignant germ cell tumor characterized by the presence of large germ cells with abundant cytoplasm resembling epithelial cells, geographic necrosis, high mitotic activity, and pseudoglandular and pseudopapillary structures formation. "Keratin intermediate filament proteins, keratin 8 (K8, Krt8, EndoA) and keratin 18 (K18, Krt18, EndoB) were first identified in liver and as markers of mouse embryonal carcinoma (EC) and embryonic stem (ES) cell differentiation." (PMID 18941637, 2008).
glioma (2 papers, 2018 to 2019). A benign or malignant brain and spinal cord tumor that arises from glial cells (astrocytes, oligodendrocytes, ependymal cells). "First, that there is cytokeratin-18 in brain; and this has been found in a study of patients with pituitary adenomas, and in a study of rats with glioma." (PMID 29573748, 2018). "Cytokeratin-18 is present in the intracytoplasmic cytoskeleton of epithelial tissue, but CCCK-18 has also been found in the brain of rats with glioma and in the brain of patients with pituitary adenomas." (PMID 31658711, 2019).
graft versus host disease (2 papers, 2009 to 2014). An immune system disorder that occurs after allogeneic hematopoietic stem cell transplant and is a reaction of donor immune cells against host tissues. "KRT18 expression has also been suggested to play a role in the immunosuppressive potential of graft-versus-host disease (GVHD)." (PMID 24780490, 2014).
nasopharyngeal carcinoma (2 papers, 2014 to 2019). A carcinoma arising from the nasopharyngeal epithelium. "By silencing EZH2, the mRNA expression levels of E-cadherin and Keratin 18 increased by 177 and 158%, respectively; while mesenchymal markers, β-catenin and N-cadherin, decreased by 18.04 and 41.18%, respectively, in nasopharyngeal carcinoma cells." (PMID 25295088, 2014).
skin carcinoma (2 papers, 2022 to 2023). "For example, previous studies have reported that KRT8, KRT18, and KRT19 are expressed in most cancers, including skin cancer, whereas our analysis revealed that their expression is low in skin cancer samples." (PMID 35267493, 2022).
staphylococcus aureus infection (2 papers, 2022 to 2024). An infectious process in which the bacteria Staphylococcus aureus is present. "KRT18 is also involved in the cytoskeletal signaling pathway, estrogen signaling pathway, and staphylococcus aureus infection pathway." (PMID 35456240, 2022). "For instance, Staphylococcus aureus infection (bta05150) pathway was significantly enriched by genes (e.g., CATHL2, CATHL3, KRT18, FGG) harboring DMCs at their first exons as well as differential genes (identified by MethGET) having significant DNA methylation changes in their regulatory regions." (PMID 38486242, 2024).
thyroid cancer (2 papers, 2011 to 2021). "Although both cytokeratin-18 and vimentin expressions were observed even in undifferentiated thyroid cancer cell lines, the cytokeratin-18 expression was lost in the SAGM-grown cells." (PMID 21556376, 2011). "Next, we checked the cytokeratin-18 and vimentin expression in thyroid cancer cell lines." (PMID 21556376, 2011).
alcoholic cirrhosis (1 paper, 2025). "In alcoholic cirrhosis, inflammatory biomarkers, particularly extracellular vesicles (HR = 5.09 [2.01, 12.86]) and keratin-18 (HR = 1.77 [1.14, 2.75]), showed superior predictive value." (PMID 40969799, 2025).
arteriovenous malformations (1 paper, 2016). "If the functions of Igfn1 and Krt18 are unknown in neurons, their function in smooth muscle cells and implication in intracerebral arteriovenous malformations indicate that hypergravity could act on pericytes to modify the cerebrovascular function and hippocampus perfusion." (PMID 28082866, 2016).
carcinoid tumor (1 paper, 2013). A slow growing neuroendocrine tumor, composed of uniform, round, or polygonal cells having monotonous, centrally located nuclei and small nucleoli, infrequent mitoses, and no necrosis. "Carcinoid tumors stain positively for keratin 18, chromogranin A, and synaptophysin." (PMID 23691399, 2013).
chorioangioma (1 paper, 2014). "Positivity for CD31 and CD34 endothelial cells markers was detected as well as focal positivity for the cytokeratin 18 marker, leading to the diagnosis of placental hemangioma (chorioangioma)." (PMID 25295202, 2014).
colon adenomatous polyp (1 paper, 2019). "Only one study showed that normal colon tissues exhibited higher KRT18 expression than colon adenomatous polyp or carcinoma tissues." (PMID 31345960, 2019).
colorectal adenocarcinoma (1 paper, 2011). The most common type of colorectal carcinoma. "Some of the identified proteins, e.g. IgGF-binding protein, Cytokeratin-18, Src substrate cortactin are typically overexpressed in colorectal adenocarcinoma cells." (PMID 21849038, 2011).
cystitis (1 paper, 2016). Inflammation of the urinary bladder. "The role of apoptosis in ketamine-induced cystitis was supported using human urothelial organ cultures that showed pyknotic nuclei, karyorrhexis, and immunoreactivity with a cleaved-cytokeratin 18 antibody." (PMID 27001627, 2016).
endometrioid tumor (1 paper, 2021). A benign, borderline, or malignant epithelial tumor of the female reproductive system characterized by the presence of glands and/or cysts lined by neoplastic cells that resemble endometrial cells. "Reduced expression of CDH1 and KRT18 was significantly associated with high-grade tumors and non-endometrioid tumor histology, while increased expression CTSB, CDH2 and ZEB1 could be observed in serous tumors." (PMID 34936030, 2021).
head and neck squamous cell carcinoma (1 paper, 2025). A squamous cell carcinoma that arises from any of the following anatomic sites: lip and oral cavity, nasal cavity, paranasal sinuses, pharynx, larynx, and salivary glands. "Moreover, pharmacogenomic analyses suggest that fedratinib may exhibit utility in head and neck squamous cell carcinoma (HNSCC) exhibiting low KRT18 expression." (PMID 41476794, 2025).
large cell carcinoma (1 paper, 2021). A malignant epithelial neoplasm composed of large, atypical cells. "However, it should be noted that the KRT18 expression, which mainly characterizes LUAD, absolutely correlated with the grafting (7/7 cases, p = 0.009), corresponding to two LUAD, four LUSC, and one large cell carcinoma case." (PMID 34070013, 2021).
neutropenia (1 paper, 2022). A decrease in the number of neutrophils found in the blood. "This is the first study on cytokeratin-18 fragment M30 as an apoptosis-related prognostic marker in febrile neutropenia of hematological patients." (PMID 34255216, 2022).
non-Hodgkin lymphoma (1 paper, 2011). Distinct from Hodgkin lymphoma both morphologically and biologically, non-Hodgkin lymphoma (NHL) is characterized by the absence of Reed-Sternberg cells, can occur at any age, and usually presents as a localized or generalized lymphadenopathy associated with fever and weight loss. "Circulating biomarkers of cell death (nucleosomal DNA (nDNA) and cytokeratin 18 (CK18)), and circulating FLT3 ligand, a potential biomarker of myelosuppression, were assessed before and serially after standard chemotherapy in 49 patients with Hodgkin and non-Hodgkin lymphoma." (PMID 21245866, 2011).